SLC20A1 (solute carrier family 20 member 1)
Diseases named in the same sentence as SLC20A1 in open-access papers:
SLC20A1 is named in the same sentence as 41 diseases in open-access papers, as found by Europe PMC text mining. Sharing a sentence is not in itself a finding about the gene and the disease. The quoted sentences say what the papers report.
breast carcinoma (5 papers, 2022 to 2025). "More advanced stages of tumor luminal A breast cancer were associated with increased SLC20A1 expression, according to a previous investigation." (PMID 38412319, 2024). "To assess the potential prognostic implications of SLC20A1 expression in detail, we evaluated its association with tumor stage and endocrine therapy outcomes in patients with luminal A and luminal B breast cancers in the present study." (PMID 35605014, 2022). "The expression of SLC20A1 is high in ER+ breast cancer and has been previously found to associated with poor prognosis." (PMID 35605014, 2022). "High SLC20A1 expression is associated with poor prognoses in basal-like breast cancers, longue cancer and esophageal adenocarcinoma." (PMID 35321944, 2022). "In the present study, we examined the possible association of SLC20A1 expression with tumor staging, endocrine therapy and chemotherapy in the luminal A and luminal B subtypes of breast cancer." (PMID 35605014, 2022). "And the possible association between SLC20A1 expression at tumor stages and clinical outcomes in patients with breast cancer remains poorly defined." (PMID 35605014, 2022). "Apart from breast cancer, it has been reported that a high SLC20A1 expression is associated with poor prognoses in pancreatic cancer using Kaplan-Meier and COX hazards analyses of overall survival." (PMID 35605014, 2022). "Targeted siRNA knockdown of SLC20A1 in breast cancer cells was tested for its influence on tumor sphere formation and cell viability." (PMID 38412319, 2024). "Solute carrier family 20 member 1 (SLC20A1) is a sodium/inorganic phosphate symporter that has been proposed to be a viable prognostic marker for the luminal A and luminal B types of ER+ breast cancer." (PMID 35605014, 2022). "We showed that patients with higher levels of SLC20A1 expression (SLC20A1high) exhibited poorer clinical outcomes in those with tumor stage I luminal A breast cancer." (PMID 35605014, 2022). "It has been previously shown that the levels of SLC20A1 expression in ER+ breast cancer tissues are higher compared with those in normal tissues, where high SLC20A1 expression is associated with poorer clinical outcomes." (PMID 35605014, 2022). "We have previously shown that SLC20A1 knockdown suppressed tumor sphere formation by aldehyde dehydrogenase 1-positive CSCs from claudin-low and basal-like type breast cancer." (PMID 35605014, 2022). "Moreover, this SLC20A1 high subset of individuals showed worse responses to endocrine treatment, particularly in breast cancer luminal A and B subtypes." (PMID 38412319, 2024). "In recent years, investigations showed the vital role that SLC20A1 plays in the progression of various tumors, such as pituitary tumors, breast cancer, and tongue SCC, indicating the high expression of SLC20A1 in many tumors and its potential association with unfavorable prognosis." (PMID 38412319, 2024). "Additionally, we analyzed the possible relationship between late recurrence and SLC20A1 expression in patients with luminal A and luminal B breast cancer after endocrine therapy." (PMID 35605014, 2022). "Patients tested to be in the SLC20A1high group at the time of diagnosis also showed a higher incidence of recurrence compared with those with lower expression levels of SLC20A1, at >15 years for luminal A breast cancer and at 10–15 years for luminal B breast cancer." (PMID 35605014, 2022). "In addition, we analyzed the relationship between SLC20A1 expression and late recurrence in patients with luminal A and luminal B breast cancer following endocrine therapy." (PMID 35605014, 2022). "Therefore, SLC20A1 may contribute to the maintenance of dormant CSCs and lead to late recurrence in luminal A and luminal B breast cancer." (PMID 35605014, 2022).
breast carcinoma (continued). "In the present study, therefore, to assess the role of SLC20A1 expression in ER+ breast cancer subtypes in detail, we analyzed a METABRIC dataset that included the gene expression data from 1904 breast cancer patients." (PMID 35605014, 2022). "In addition, SLC20A1 siRNA knockdown has been reported to reduce cell viability in MCF7 cells, which was derived from the luminal A subtype of breast cancer." (PMID 35605014, 2022). "Although Slc20a1 is not a specific CRC marker, its overexpression has been related with a poor prognosis of prostate cancer and breast cancer." (PMID 40284221, 2025).
somatotroph adenomas (4 papers, 2021 to 2025). "The expression of SLC20A1 (phosphate transporter 1) in a study on somatotroph adenomas was associated with the activation of the Wnt/β-catenin signaling pathway." (PMID 33671384, 2021). "In somatotroph adenomas, a positive correlation was noted for tumor recurrence, size, and invasiveness with SLC20A1 levels." (PMID 38412319, 2024). "SLC20A1 (Solute Carrier Family 20 Member 1, phosphate transporter 1) overexpression is correlated with tumor size, invasive behavior, and tumor recurrence of somatotroph adenomas." (PMID 40362297, 2025).
glioblastoma (3 papers, 2021 to 2022). The most malignant astrocytic tumor (WHO grade IV). "Sodium-dependent phosphate transporter 1 (slc20a1) is described to be over-expressed in high grade gliomas and Integrin-linked protein kinase (ilk) to promote glioblastoma invasion." (PMID 34646273, 2021).
bladder exstrophy-epispadias complex (2 papers, 2020 to 2023). "Additionally, we resequenced SLC20A1 in 690 individuals with bladder exstrophy-epispadias complex (BEEC) including 84 individuals with cloacal exstrophy." (PMID 32850778, 2020).
esophageal adenocarcinoma (2 papers, 2022 to 2024). A malignant tumor with glandular differentiation arising predominantly from Barrett mucosa in the lower third of the esophagus. "In esophageal adenocarcinoma, SLC20A1 was considered an independent prognostic indicator for relapse-free survival." (PMID 38412319, 2024).
glioma (2 papers, 2020 to 2021). A benign or malignant brain and spinal cord tumor that arises from glial cells (astrocytes, oligodendrocytes, ependymal cells). "Furthermore, the expression levels of several genes (PLOD3, SLC20A1, ADAM9, FBLIM1, SPOCD1, P4HB, PROS1 and SELENON) were positively correlated with glioma grades." (PMID 32091665, 2020).
pancreatic cancer (2 papers, 2020 to 2022). "Similarly, LDHA, EPS8, SLC20A1 and ARNTL2 expression are also related to metastasis or shorter survival in pancreatic cancer." (PMID 32310997, 2020).
preeclampsia (2 papers, 2020 to 2024). Preeclampsia is a hypertensive disorder of pregnancy that is characterized by new-onset hypertension with proteinuria presenting after 20 weeks of gestation, and depending on mild or severe forms may initially present with severe headache, visual disturbances, and hyperreflexia. "The biomarkers CGB5, LEP, LRRC1, PAPPA2, and SLC20A1 offer varying prospects for predicting preeclampsia." (PMID 39544937, 2024). "In early preeclampsia (PE), placental expression of the sodium-dependent phosphate transporters Slc20a1 and Slc20a2 is highly reduced; yet in late PE, Slc20a2 is significantly increased." (PMID 32722465, 2020). "Similarly, reduced levels of SLC20A1 and SLC20A2 in human placentas have been linked to early-onset preeclampsia, indicating that disruptions in these proteins can affect immune regulation and angiogenesis." (PMID 39544937, 2024). "Conversely, the roles of LRRC1 and SLC20A1 in preeclampsia remain unclear, necessitating further research." (PMID 39544937, 2024). "Recent research on SLC20A1 (the phosphate transporter PiT1) has illuminated its complex role in various biological processes, yet its direct connection to preeclampsia has not been fully explored." (PMID 39544937, 2024).
Anxiety (1 paper, 2024). Intense feelings of nervousness, tension, or panic often arise in response to interpersonal stresses. "We demonstrate that although both Slc20a1 and Slc20a2 impact spatial and episodic memory, only Slc20a1 affects contextual memory, while only Slc20a2 is linked to anxiety-related phenotypes." (PMID 38195526, 2024).
breast tumors (1 paper, 2024). "SLC20A1 was shown to be important in cancer development and to contribute to clinical outcomes in individuals with ER+, claudin-low, and basal-like breast tumors." (PMID 38412319, 2024).
calcification (1 paper, 2018). Process by which organic tissue becomes hardened by the physiologic deposit of calcium salts. "It is difficult to ascertain if cerebral calcification were only related to 21 trisomy or if the concomitant presence of the SLC20A1 variant played also a role." (PMID 30111349, 2018).
chronic kidney disease (1 paper, 2026). Impairment of the renal function secondary to chronic kidney damage persisting for three or more months. "Omental arterioles of children on low-glucose-degradation-product (GDP) PD showed higher SLC20A1 expression vs. stage 5 chronic kidney disease (CKD5) and healthy controls." (PMID 42074321, 2026).
cloacal exstrophy (1 paper, 2020). A major birth defect representing the severe end of the spectrum of the exstrophy-epispadias complex (EEC) characterized by omphalocele, exstrophy, imperforate anus and spinal defects (also referred to as the OEIS complex), often associated with other malformations. "Furthermore, we performed immunohistochemistry of an unaffected 6-week-old human embryo and detected SLC20A1 in the urinary tract and the abdominal midline, structures implicated in the pathogenesis of cloacal exstrophy." (PMID 32850778, 2020). "The recent identification of SLC20A1 as a monoallelic candidate gene for cloacal exstrophy further suggests its involvement in the urinary tract and urorectal development." (PMID 32850778, 2020). "The recent identification of the phosphate transporter SLC20A1 as a candidate gene for cloacal exstrophy (CE) (OMIM 258040) suggests its involvement also in the lower urinary tract and urorectal development." (PMID 32850778, 2020).
fibrosarcoma (1 paper, 2022). A malignant mesenchymal fibroblastic neoplasm affecting the soft tissue and bone. "An additional four previously identified genes (RAPGEF2, SLC20A1, CO5A, TIGD2) were also more highly expressed in fibrosarcomas, but the comparison did not exceed the cutoff for significance used in the present study." (PMID 36099287, 2022).
hyperphosphatemia (1 paper, 2023). Abnormally high level of phosphate in the blood. "In Nx6 animals that exhibited hyperphosphatemia, we found Slc20a1/2, Xpr1, and Mapk1/3 to be downregulated, suggesting opposite effects of longer bone exposure on increased extracellular Pi in the regulation of gene expression in in vitro vs. short-term in vitro studies." (PMID 37108433, 2023).
hypopharyngeal cancers (1 paper, 2023). Carcinoma, predominantly squamous cell, arising from the epithelial cells of the hypopharynx. "We validated the prognostic model using an external validation dataset from TCGA, selecting mRNA sequencing (mRNA-seq) and miRNA-seq data for OSCC (including laryngeal and hypopharyngeal cancers) and screening the matrix data for SLC20A1, PITX2, hsa-mir-135b, hsa-mir-377, and hsa-let-7c." (PMID 36741263, 2023).
Kidney Cyst (1 paper, 2021). Abnormal fluid filled sac within the kidney, either acquired or congenital. "Interestingly, another member of the Solute Carrier Family, SLC20A1, has been suggested to be involved in cloacal malformations and kidney cysts in humans, supported by zebrafish studies." (PMID 34573432, 2021).
memory impairment (1 paper, 2024). "Furthermore, mice targeted for both Slc20a1 and Otof did not exhibit any memory impairments, as shown in the NOR and MWM behavioral tasks, contrary to the Slc20a1-downregulated mice." (PMID 38195526, 2024).
oral cancer (1 paper, 2025). "Screening of the data revealed eight TRGs (TGFB3, LTBP2, BMP2, TGFB1, ACVR1, CDK9, SLC20A1, and SMURF2) with non-zero coefficients, indicating their association with the prognosis of oral cancer patients." (PMID 38698292, 2025).
Pancytopenia (1 paper, 2022). An abnormal reduction in numbers of all blood cell types (red blood cells, white blood cells, and platelets). "In accordance, the decline of the HSC pool size, HSC apoptosis, and pancytopenia were further aggravated in the Slc20a1+/− mice compared to their WT littermates post IR." (PMID 36014901, 2022).
tongue cancer (1 paper, 2021). A malignant neoplasm affecting the tongue. "Previous studies have reported that the expression of LEPR 42, PFKM 43, 44, PGK1 45, 46, CYP19A1 47, 48, SLC20A1 49, and ZC3H12D 50 were associated with tumorigenesis and progression in various tumor types, which support the further identification and exploring in tongue cancer." (PMID 33758601, 2021). "PGK1, SLC20A1, LEPR, CYP19A1, ZC3H12D, and PFKM were found to be independent predictors in tongue cancer." (PMID 33758601, 2021).
viral infections (1 paper, 2013). "SLC20A1 may also function as a retroviral receptor as it confers susceptibility to certain viral infections in human cells." (PMID 23251289, 2013).
tumor (15 papers, 2020 to 2026). "Tumor development increased pik3cd and slc20a1 expression with respect to the healthy control group." (PMID 40284221, 2025). "This study projects to investigate the impact of SLC20A1 in tumor progression, prognostic value, molecular mechanism and treatment response in HNSCC." (PMID 38412319, 2024). "Four of them had significant expression in immune cells, SLC20A1 with KRT17 was more expressed in malignant tumor cells and ITGA1 was more expressed in mesenchymal cells." (PMID 39127853, 2024). "More research is needed to determine SLC20A1's precise role in the tumor-immune milieu, however, since the infiltrative immunological landscape of HNSCC has not been fully described to this point." (PMID 38412319, 2024). "Several studies suggest that SLC20A1 are upregulated in tumor cells and have been considered to be important promoters of tumor progression." (PMID 33758601, 2021). "In this study, SLC20A1 expression was related to tumor size, invasive behavior, and tumor recurrence." (PMID 33671384, 2021). "Beyond the Pi transport, SLC20A1 was also demonstrated for function in tumor cell proliferation and apoptosis." (PMID 33758601, 2021). "Accordingly, SLC20A1 might act as a novel biomarker in tumor progression and immune environment in HNSCC." (PMID 38412319, 2024). "At present, some studies explored the role of SLC20A1 in different tumor species." (PMID 38412319, 2024). "SLC20A1, a sodium-phosphate symporter involved in tumor formation by HeLa cells in xenografted mice, has a negative coefficient in all datasets, suggesting its expression is inhibited in CRC, although its significance in CRC is currently unknown." (PMID 38243058, 2024). "Therefore, we conclude that high expression of SLC20A1 can remarkably induce tumor cells to invade, migrate, and proliferate, additionally showing the unfavorable prognosis of this biomarker in cases with HNSCC." (PMID 38412319, 2024). "Although this investigation provides results that might aid to a better comprehension of SLC20A1 expression value in tumor progression and prognosis in HNSCC, different limitations should be highlighted." (PMID 38412319, 2024). "SLC20A1 was highly expressed in tumour samples, whereas hsa-let-7c had low expression." (PMID 36741263, 2023). "Although, these previous findings suggest the potential prognostic value of using SLC20A1 expression for predicting late recurrence in patients with ER+ at early tumor stages, its relationship with tumor stage or endocrine therapy outcomes, and late recurrence remain to be clarified." (PMID 35605014, 2022). "Statistical difference in SLC20A1 expression among the tumor stages in the ER+, luminal A and luminal B subtypes also could not be found." (PMID 35605014, 2022). "We first compared the levels of SLC20A1 expression in tissues among the various tumor stages." (PMID 35605014, 2022). "Moreover, SLC20A1 depletion leads to an increase in the phosphorylation of p38, which is reported to delay the G2/M transition under various environmental stress conditions and inhibit cell proliferation and tumour progression." (PMID 36676849, 2022). "Our study identified four critical DEGs (CXCL8, PSMC2, APP, and SLC20A1) that demonstrated high performance in identifying CRC in diverse populations and ethnicities, covering a range of tumor stages and histologic grades." (PMID 38243058, 2024). "TRIO, SLC20A1, MAP4K4 and ERRF1 genes which are upregulated in high PPS20 patients, were also shown to be involved in cellular proliferation and/or tumor growth." (PMID 32310997, 2020). "Box-plot analysis revealed no statistical difference in SLC20A1 expression among the tumor stages." (PMID 35605014, 2022).
tumor (continued). "Therefore, it is speculated that a decrease in SLC20A1 expression could reduce the activation of the TNF/TNFR2 signaling pathway, thereby inhibiting Tregs, restoring tumor immune response, and eliminating the tumor." (PMID 38412319, 2024).
infection (5 papers, 2011 to 2024). The state of being infected such as from the introduction of a foreign agent such as serum, vaccine, antigenic substance or organism. "Our data suggest that TLF-II effectively reduces bacterial escape may through inhibiting SLC20A1 expression and protecting Rab27b-labeled vesicles, lowering the risk of recurrent infection." (PMID 38638825, 2024). "To resolve the role of SLC20A1 in GALV entry and assess the effects of productive infection on SLC20A1/2, we used replication-competent A-MLV and GALV containing enhanced green fluorescence protein (eGFP) as a reporter." (PMID 21729311, 2011).
cancer (3 papers, 2019 to 2024). A tumor composed of atypical neoplastic, often pleomorphic cells that invade other tissues. "In this study, the results indicated that SLC20A1 overexpression had markedly a positive correlation with numerous types of cancer." (PMID 38412319, 2024). "Among the DENR-regulated transcripts were several relevant to cancer, such as Klhdc8a, Etaa1, Map2k5, Slc20a1 or Vegfd." (PMID 30982898, 2019). "In addition, inhibiting SLC20A1 has been shown to delay cell cycle progression and impair mitosis and cytokinesis and cell proliferation in cancer cells." (PMID 35605014, 2022). "Therefore, it is also crucial to perform similar analyses of SLC20A1 in the cohorts of other types of cancer." (PMID 35605014, 2022). "Based on our findings, SLC20A1 is upregulated in HNSCC tissues and may serve as a poor prognostic indication for this disease by encouraging cancer cells to invade, migrate, and proliferate." (PMID 38412319, 2024).
immune dysfunction (1 paper, 2024). "Furthermore, we identified that SLC20A1 overexpression is correlated with more immune exclusion and immune dysfunction and lower TIDE score." (PMID 38412319, 2024).
SLC20A1 also shares sentences with these, for which no sentence is quoted: exstrophy-epispadias complex (2 papers); head and neck squamous cell carcinoma (2); astrocytoma (1); bone tumor (1); Calcific Aortic Valve Disease (1); colon cancer (1); corticotrophic adenomas (1); diabetes (1); gout (1); gynecologic cancer (1); hepatocellular carcinoma (1); lung carcinoma (1); pituitary tumor (1); prostate carcinoma (1); tongue SCC (1).